RMRP (RNA component of mitochondrial RNA processing endoribonuclease)
Diseases named in the same sentence as RMRP in open-access papers (continued):
Sharing a sentence is not in itself a finding about the gene and the disease.
glioma (5 papers, 2018 to 2023). A benign or malignant brain and spinal cord tumor that arises from glial cells (astrocytes, oligodendrocytes, ependymal cells). "Moreover, RMRP loss inhibited β-catenin expression by up-regulating ZNRF3 in glioma cells." (PMID 34657141, 2021). "RMRP expression was recently investigated in low-grade (grade I-II) to high-grade (grade III-IV) glioma cell lines and tissues." (PMID 37332990, 2023). "In summary, these data revealed that ZNRF3 knockdown weakened the effects of RMRP depletion on glioma cell proliferation, apoptosis, and TMZ resistance." (PMID 34657141, 2021). "The inhibition of Wnt/β-catenin signaling pathway by XAV-939 weakened RMRP-mediated TMZ resistance in glioma cells." (PMID 34657141, 2021). "In this project, our data revealed that RMRP was highly expressed in glioma tissues and RMRP knockdown inhibited glioma cell proliferation and promoted glioma cell apoptosis, which was in accordance with a previous study." (PMID 34657141, 2021). "Taken together, our data demonstrated that RMRP was highly expressed in glioma tissues versus normal brain tissues." (PMID 34657141, 2021). "In other words, RMRP knockdown inhibited glioma cell proliferation, facilitated glioma cell apoptosis, and weakened the resistance of glioma cells to TMZ through up-regulating ZNRF3." (PMID 34657141, 2021). "Knockdown of RMRP significantly decreased the proliferation of glioma cell lines in vitro." (PMID 37332990, 2023). "Hence, the roles and molecular basis of RMRP in glioma tumorigenesis and TMZ resistance were further investigated in the subsequent experiments." (PMID 34657141, 2021). "RMRP exerted its functions by down-regulating ZNRF3 in glioma cells." (PMID 34657141, 2021). "Moreover, co-expression relationships of RMRP and the top 50 down-regulated genes in glioma were predicted through the GEPIA database." (PMID 34657141, 2021). "RMRP depletion hindered cell proliferation, induced cell apoptosis, and reduced TMZ resistance in glioma cells, and curbed the growth of TMZ-treated glioma xenograft tumors in vivo, hinting that RMRP loss or inhibition could be used to mitigate TMZ resistance." (PMID 34657141, 2021). "Moreover, ZNRF3 depletion abolished the inhibitory effect of RMRP knockdown on cell survival in TMZ-treated parental glioma cells (U251 and LN229) and TMZ-resistant glioma cells (U251/TMZ and LN229/TMZ)." (PMID 34657141, 2021). "Also, a recent study demonstrated that RMRP was highly expressed in glioma tissues and RMRP knockdown led to the marked reduction of cell proliferative, migratory and invasive abilities and a notable increase of cell apoptotic rate in glioma." (PMID 34657141, 2021). "Additionally, ZNRF3 downregulation markedly weakened the effects of RMRP knockdown on glioma cell proliferation, apoptosis, and TMZ resistance." (PMID 34657141, 2021). "In addition, Feng et al33 showed that RMRP expression was up‐regulated in glioma samples compared to normal brain samples." (PMID 30156374, 2018). "Down‐regulation of RMRP inhibited glioma cell growth, invasion and migration." (PMID 30156374, 2018). "Furthermore, lncRNA RMRP upregulation is significantly associated with advanced tumor grade and low Karnofsky Performance Score (KPS), indicating RMRP up-regulation may be involved in glioma progression." (PMID 37332990, 2023). "Furthermore, our data revealed that RMRP depletion led to the notable reduction of TMZ IC50 values in U251, LN229, U251/TMZ, and LN229/TMZ cells, suggesting that RMRP loss weakened TMZ resistance in parental and TMZ-resistant glioma cells." (PMID 34657141, 2021). "Hence, we further investigated whether the RMRP/ZNRF3 axis could regulate the Wnt/β‐catenin signaling pathway in glioma cells." (PMID 34657141, 2021). "This is the first study to demonstrate that RMRP knockdown could weaken TMZ resistance in glioma." (PMID 34657141, 2021). "Thus, we further investigated whether β-catenin could regulate lncRNA RMRP expression by TCF4 in glioma cells." (PMID 34657141, 2021).
glioma (continued). "However, it remains unknown whether RMRP is involved in the regulation of TMZ resistance in glioma." (PMID 34657141, 2021). "In summary, these outcomes presented that RMRP knockdown curbed cell proliferation, facilitated cell apoptosis, and reduced TMZ resistance in glioma cells." (PMID 34657141, 2021). "Thus, we further investigated whether RMRP could regulate ZNRF3 expression in glioma." (PMID 34657141, 2021). "In this text, we investigated the effects of RMRP knockdown on glioma cell proliferation, apoptosis, and TMZ resistance in vitro and the growth of TMZ-treated glioma xenograft tumors in vivo." (PMID 34657141, 2021). "In conclusion, RMRP/ZNRF3 axis and Wnt/β-catenin signaling formed a positive feedback loop to regulate TMZ resistance in glioma." (PMID 34657141, 2021). "RMRP knockdown curbed cell proliferation, facilitated cell apoptosis and reduced TMZ resistance in glioma cells, and hindered the growth of TMZ-treated glioma xenograft tumors." (PMID 34657141, 2021). "Moreover, GEPIA database analyses revealed that expression levels of RMRP, HOXA-AS3, and CASC9 were notably up-regulated in glioma tissues than in normal tissues." (PMID 34657141, 2021). "Furthermore, β-catenin increase markedly facilitated RMRP expression by TCF4 and TCF4 promoted RMRP expression by directly binding with the RMRP promoter region in glioma cells." (PMID 34657141, 2021). "Moreover, we demonstrated that RMRP depletion reduced the resistance of glioma cells to TMZ in vitro and inhibited the growth of TMZ-treated glioma xenograft tumors in vivo." (PMID 34657141, 2021). "Moreover, we demonstrated that RMRP/ZNRF3 axis and Wnt/β‐catenin signaling pathway could form a positive feedback loop to regulate TMZ resistance in glioma." (PMID 34657141, 2021). "Given the association of tumor recurrence and drug resistance, expression patterns of RMRP, HOXA-AS3, and CASC9 were examined in tumor tissues isolated from glioma patients without any treatment (n = 20) and glioma patients suffered from recurrence post-treatment (n = 12)." (PMID 34657141, 2021).
ovarian carcinoma (4 papers, 2022 to 2025). A malignant neoplasm originating from the surface ovarian epithelium. "In our recent study, we found that PHGDH was upregulated in epithelial ovarian cancer and was regulated by lncRNA RMRP and DDX3X in translational level." (PMID 36105480, 2022). "It indicates a critical function of RMRP in regulating ovarian cancer development, especially PTX resistance and glycolysis." (PMID 35132320, 2022). "We observed that RMRP was highly expressed in the ovarian cancer samples, in which the expression of RMRP was elevated in the PTX-resistant patients compared with the PTX-sensitive patients." (PMID 35132320, 2022). "RMRP promotes ovarian cancer invasion via RAB31-dependent MMP secretion." (PMID 40565315, 2025). "Meanwhile, RMRP was upregulated in PTX-resistant ovarian cancer cell lines." (PMID 35132320, 2022). "Meanwhile, the miR-580-3p/MICU1 axis may just be one of the mechanisms of RMRP-regulated ovarian cancer and other downstream factors should be explored in future investigations." (PMID 35132320, 2022). "Firstly, we evaluated the expression of RMRP in clinical ovarian cancer samples." (PMID 35132320, 2022). "Targeting RMRP may serve as a potential therapeutic strategy for the treatment of PTX-resistant ovarian cancer patients." (PMID 35132320, 2022). "Our data further showed that RMRP contributes to PTX resistance and glycolysis in ovarian cancer cells." (PMID 35132320, 2022). "Functionally, we found that the silencing of RMRP by siRNA significantly enhanced the PTX sensitivity of PTX-resistant ovarian cancer cells, in which the IC50 of PTX was reduced by RMRP depletion." (PMID 35132320, 2022). "RMRP-regulated PTX resistance and progression of ovarian cancer cells at least partly by targeting the miR-580-3p/MICU1 axis." (PMID 35132320, 2022). "Our finding provides new insights into the mechanism by which RMRP regulates PTX resistance and glycolysis of ovarian cancer by modulating the miR-580-3p/MICU1 axis." (PMID 35132320, 2022). "Thus, we concluded that RMRP contributes to PTX resistance and glycolysis of ovarian cancer by enhancing MICU1 expression through sponging miR-580-3p." (PMID 35132320, 2022).
cardiac hypertrophy (3 papers, 2021 to 2024). "For instance, H19 and RMRP are involved in heart failure progression, while BDNF-AS is a cardiomyocyte damage-associated gene; SNHG7 is a cardiac hypertrophy regulator." (PMID 35415316, 2022). "Both H19 and RMRP engage in cardiac hypertrophy and heart failure progression, while a BDNF-AS downregulation can activate BDNF, VEGF, and Akt, and thus rescue hypoxia/reoxygenation-induced damage in cardiomyocyte." (PMID 35415316, 2022). "RMRP was dysregulated in both end- and non-end-stage HF patients and mouse model of cardiac hypertrophy." (PMID 33996836, 2021).
depression (3 papers, 2021 to 2022). "Moreover, they found reduced expression of RMRP in the blood of a widely used corticosterone-induced mouse model of depression, corroborating the observations in MDD patients." (PMID 34276306, 2021). "Finally, expression of RMRP has been significantly down-regulated in patients with major depressive disorder compared with normal individuals in correlation with severity of depression." (PMID 33996836, 2021).
DiGeorge syndrome (3 papers, 2014 to 2021). "DiGeorge syndrome (del22q11) was most common, followed by mutations in CTLA4, RMRP, IKZF1, and KMT2D." (PMID 33968040, 2021).
hepatocellular carcinoma (3 papers, 2021 to 2023). A malignant tumor that arises from hepatocytes. "The results of in vitro and in vivo studies consistently verify this function for RMRP with a single exception in the hepatocellular carcinoma." (PMID 33996836, 2021). "However, another in vivo study demonstrated the opposite role for RMRP in the pathogenesis of hepatocellular carcinoma through modulation of miR-766." (PMID 33996836, 2021).
myocardial ischemia (3 papers, 2020 to 2023). A disorder of cardiac function caused by insufficient blood flow to the muscle tissue of the heart. "Among the dysregulated lncRNAs, RMRP was recently found to be upregulated by hypoxia in cardiomyocytes, and to aggravate myocardial ischemia-reperfusion injury by sponging miR-206 to target ATG3 expression." (PMID 31927529, 2020).
neuroblastoma (3 papers, 2019 to 2023). Neuroblastoma (NB) is the most common solid, extracranial childhood tumor. "RMRP can interact with miR‐206 in neuroblastoma cells, such as sequestering miR‐206 from TACR1 as a ceRNA for miR‐206, implying that RMRP regulates the miR‐206/TACR1 axis to play an oncogenic role in neuroblastoma gene action." (PMID 35592755, 2022). "Inhibition of ERK1/2 pathway and TACR1 reduces the function of RMRP to promote proliferation in neuroblastoma cells." (PMID 35592755, 2022). "The knockdown of RMRP inhibits neuroblastoma xenograft growth by modulating the miR‐206 or TACR1 axis and inactivating the ERK1/2 pathway in vivo." (PMID 35592755, 2022). "Furthermore, TACR1 overexpression induces the ERK1/2 axis and reverses the effects of RMRP downregulation on neuroblastoma cell growth." (PMID 35592755, 2022). "In neuroblastoma cells, RMRP knockdown can inhibit invasion and migration." (PMID 35592755, 2022). "The inhibition of the lncRNA molecule could restore the proliferation and migration of human neuroblastoma SH-SY5Y cells, inferring the possibility that therapies targeting RMRP could not only increase the viability of nerve cells but also promote the migration of the nerve cells." (PMID 30926681, 2019).
non-small cell lung carcinoma (3 papers, 2021 to 2024). A group of at least three distinct histological types of lung cancer, including non-small cell squamous cell carcinoma, adenocarcinoma, and large cell carcinoma. "Furthermore, RMRP has been identified as an upregulated lncRNA in non-small cell lung cancer, and it acts mainly on tumor cells in part by forcing cell proliferation." (PMID 38722543, 2024). "RMRP is upregulated in non-small cell lung cancer (NSCLC) and promotes proliferation, invasion, and migration by interacting and recruiting YBX1 to the TGF-β receptor 1 (TGFBR1) promoter, upregulating TGFBR1 and enhancing the TGFBR1/SMAD2/SMAD3 growth signaling pathway." (PMID 36754845, 2023). "In addition, RMRP might promote cell proliferation, migration, and invasion in non-small-cell lung cancer via sponging miR-1a-3p." (PMID 34512545, 2021).
anauxetic dysplasia (2 papers, 2010 to 2022). A spondyloepimetaphyseal dysplasia that is characterized by the prenatal onset of extreme short stature, an adult height of less than 85 cm, hypodontia, and mild mental retardation. "Apart from CHH, mutations of RMRP (usually in different nucleotides of the RNA molecule) cause other three skeletal disorders: metaphyseal dysplasia without hypotrichosis (MDWH), kyphomelic dysplasia, and anauxetic dysplasia." (PMID 21078154, 2010).
colon cancer (2 papers, 2018 to 2021). "For example, in multiple lymphoma, c-Myc promotes the transcription of RMRP24, whereas in colon cancer, β-catenin enhances RMRP expression." (PMID 33846370, 2021). "We noted that 11 lncRNAs, SCARNA10, RPPH1, LINC01419, ERVH48-1, RMRP,CH507-513H4.3, MIR205HG, CH507-513H4.6, LINC00400, RP11-774D14.1 and AC006050.2, were also differentially expressed in colon cancer samples compared with the normal samples." (PMID 29420609, 2018).
coronary artery disease (2 papers, 2021 to 2024). "The purpose of this study was to investigate the effect of the RNA component of mitochondrial RNA-processing endoribonuclease (RMRP) on the degree of coronary artery lesions and prognosis in patients with coronary artery disease (CAD)." (PMID 38907341, 2024).
Sepsis (2 papers, 2021). Sepsis is defined as life-threatening organ dysfunction caused by a dysregulated host response to infection. "Up-regulation of RMRP reduced LPS-induced damage, apoptosis and mitochondrial damage and LPS-induced sepsis." (PMID 34956235, 2021). "Downregulation of RMRP inhibited inflammatory response and apoptosis in sepsis-induced AKI." (PMID 34956235, 2021). "RMRP regulated cardiomyocyte apoptosis and inhibited Lipopolysaccharide-induced sepsis." (PMID 33996836, 2021).
steatosis (2 papers, 2022 to 2025). Increased lipid within the cytoplasm of cells. "RMRP inhibition improved the pathological condition and liver function indices associated with lipid accumulation in the hepatic tissues of rats with NAFLD while alleviating steatosis and reducing triglyceride secretion in AML-12 cells treated with free fatty acids (FFAs)." (PMID 40141450, 2025). "In addition, RMRP was recently demonstrated to be up-regulated in liver of patients affected by non-alcoholic fatty liver disease (NAFLD); its inhibition decreased steatosis and lipid deposition in a NAFLD rat model." (PMID 36430946, 2022).
acute myocardial infarction (1 paper, 2024). Necrosis of the myocardium, as a result of interruption of the blood supply to the area. "The expression of RMRP in hypoxia-induced acute myocardial infarction cells increased, and down-regulation of RMRP could significantly reduce hypoxia-induced inflammation and injury." (PMID 38907341, 2024).
adenoma (1 paper, 2024). A neoplasm arising from the epithelium. "Noteworthy, the numbers of RNA interactors of some MP-RNAs (WDR62, TGFBR3, RN7SL5P, RMRP, MIR663AHG, AJ009632.2, CDKL1, OPRD1, PLOD1, AL117692.1, ATP13A2, EPB41) in cancer tissue were significantly increased compared with that in paracancer and adenoma." (PMID 38773399, 2024).
Artemis deficiency (1 paper, 2024). "Sixpatients had ADA deficiency, 3 had IL2RG deficiency, 3 had CD3 Delta deficiency, 2 had Artemis deficiency (affecting DCLRE1C), and 1 each had variants impacting NHEJ1, TRAC, RAC2, and RMRP." (PMID 39062699, 2024).
cholangiocarcinoma (1 paper, 2021). A carcinoma that arises from the intrahepatic biliary tree (intrahepatic cholangiocarcinoma) or from the junction, or adjacent to the junction, of the right and left hepatic ducts (hilar cholangiocarcinoma). "In the cholangiocarcinoma cells, up-regulation of RMRP is associated with down-regulation of miR-217, a miRNA that is sequestered by RMRP." (PMID 33996836, 2021). "RMRP silencing can suppress proliferation of cholangiocarcinoma cells, stimulate apoptosis in these cells, and block them in the G0/G1 stage." (PMID 33996836, 2021).
coronary artery stenosis (1 paper, 2023). "The results revealed an expression signature consisting of the upregulation of RMRP (p < 0.01) and downregulations of THRIL (p < 0.01) and HIF1A (p < 0.01) among patients with a positive thallium stress test and no significant coronary artery stenosis within 6 months after baseline treatment." (PMID 37238718, 2023).
disc degeneration (1 paper, 2018). "We showed that RMRP expression was up‐regulated in degenerated NP tissues compared to normal NP samples and RMRP expression was associated with the disc degeneration grade." (PMID 30156374, 2018). "In our study, we showed that RMRP expression was up‐regulated in degenerated NP tissues compared to normal NP samples, and higher RMRP expression was associated with the disc degeneration grade." (PMID 30156374, 2018). "Taken together, our study showed that RMRP expression was up‐regulated in degenerated NP tissues compared to normal NP samples, and higher RMRP expression was associated with the disc degeneration grade." (PMID 30156374, 2018). "In this study, we first measured the expression of RMRP in the intervertebral disc tissues and we found that RMRP expression was up‐regulated in degenerated NP tissues compared to normal NP samples, and higher RMRP expression was associated with the disc degeneration grade." (PMID 30156374, 2018). "In our study, we indicated that the expression of RMRP was up‐regulated in degenerated NP tissues compared to normal NP samples and higher RMRP expression was correlated with the disc degeneration grade." (PMID 30156374, 2018).
epilepsy (1 paper, 2022). A brain disorder characterized by episodes of abnormally increased neuronal discharge resulting in transient episodes of sensory or motor neurological dysfunction, or psychic dysfunction. "Thus, RMRP contributes to the pathogenesis of epilepsy through immune-related and -unrelated mechanisms." (PMID 36776769, 2022).
gastric tumour (1 paper, 2018). "For example, Shao et al36 found that RMRP expression was deregulated in gastric tumour." (PMID 30156374, 2018). "Moreover, Shao et al36 found that the RMRP expression was deregulated in gastric tumour." (PMID 30156374, 2018).
relapsing remitting MS (1 paper, 2022). "Consistent with our findings, a recent investigation has reported significant up-regulation of RMRP in drug-naïve relapsing remitting MS patients compared to healthy persons." (PMID 36092928, 2022).
rheumatoid arthritis (1 paper, 2021). A chronic, systemic autoimmune disorder characterized by inflammation in the synovial membranes and articular surfaces. "For instance, RMRP expression has been increased in T cells of patients with rheumatoid arthritis in correlation with disease duration." (PMID 33996836, 2021).